ZEB1 (zinc finger E-box binding homeobox 1)
Diseases named in the same sentence as ZEB1 in open-access papers (continued):
Sharing a sentence is not in itself a finding about the gene and the disease.
cancer (continued). "BRG1 loss can potentially impact cancer development, as a variety of key cellular proteins are SWI/SNF-dependent, such as the transcription factor ZEB1, which regulates E-cadherin and epithelial to mesenchymal transition (EMT)." (PMID 27486753, 2016). "ZEB1 is the main regulator of breast cancer cell plasticity enabling the reversible conversion of non‐CSCs (cancer stem cells) into CSCs." (PMID 27596438, 2016). "Similar to the findings from cancer cells, ZEB1 also oppositely regulated the growth of BEAS2B cells expressing KRASG12D or EGFRΔ722-726." (PMID 27456471, 2016). "In summary, the detection of a ‘common ZEB1/YAP target gene set' points to a new mechanism how ZEB1 drives malignant cancer progression, towards invasion, metastasis and therapy resistance." (PMID 26876920, 2016). "Here we extended those studies to demonstrate that FLASH protects ZEB1 from proteasomal degradation through a mechanism conserved in multiple cancer cell lines." (PMID 27526108, 2016). "Zeb1 represses the expression of miR-34a and miR-34b/c, and miR-34a conversely down-regulated Zeb1 and c-Myc to decrease the migration and invasion of cancer cells." (PMID 27509493, 2016). "Reduced ZEB1 expression in cancer cells resulted in de-repression of multiple ZEB1-regulated genes involved in maintenance of the epithelial phenotype." (PMID 27526108, 2016). "ZEB1 levels are controlled by miR-200 family microRNAs, the expression of which is also influenced by DNA methylation in human cancer." (PMID 26646320, 2016). "The best-characterized targets of the miR-200 family, albeit in cancer backgrounds, are the zinc finger proteins Zeb1 and Zeb230." (PMID 27767083, 2016). "ZEB1 expression in cancer cells is elevated upon signaling induction, including TGF-β and platelet-driven growth factor receptor-α signaling." (PMID 27411336, 2016). "All of the results suggest that MTs of ADPGK, PCGF6, PKP2, NUP93 and SLC22A5 can be the driver mutations controlling the cancer metastasis via affecting the EMT pathways where Snail, Claudin-1 or ZEB1 is involved." (PMID 27625789, 2016). "Overexpressed Zeb1 in turn enforced CD44 slicing that favors cancer cells acquiring stem cell features." (PMID 27840647, 2016). "Conversely, ZEB1 has been shown to strongly promote tumorigenesis and cancer metastasis by inhibiting miR-200c and miR-203 transcription." (PMID 26989421, 2016). "We found that cancers displaying a high percentage of ZEB1-positive cells exhibited a high level of VEGFA expression and CD31 density." (PMID 26882471, 2016). "Among the different transcriptional factors driving cancer EMT (i.e., EMT-TFs), ZEB1 has been found to be crucial for the induction of cancer stem cell-like properties and also for the therapeutic resistance of different cancers." (PMID 27871329, 2016). "Conversely ΔNp63α can suppress mesenchymal-like cancer migration through the miR205 dependent suppression of ZEB1/2, and the silencing of FAK." (PMID 27081041, 2016). "Previous study has found that activation of canonical Wnt/β-catenin signaling enhances in vitro motility of cancer cells by activation of ZEB1 and other activators of epithelial-to-mesenchymal transition." (PMID 27193094, 2016). "We note that known EMT drivers ZEB1, SNAI2, and TCF4 in module 5 have significant associations with survival in our pan-cancer analysis (p values 8.5 × 10–6, 5.3 × 10–4, 1.3 × 10–3 and rankings 153, 749, and 1098, respectively, out of 11,119 total genes)." (PMID 27287041, 2016). "The miR-200 family, which consists of miR-200a, miR-200b, miR-200c, miR-141, and miR-429, is known for its capability to regulate epithelial-mesenchymal transition (EMT) program in cancer cells via the posttranscriptional repression of ZEB1 or ZEB2." (PMID 26934322, 2016).
cancer (continued). "In well-differentiated areas of carcinomas, ZEB1 is expressed at low levels, but high ZEB1 expression has been found to be inversely correlated to the expression of E-cadherin in dedifferentiated, fibroblastic-like cells at the periphery of invading tumors." (PMID 27023622, 2016). "Aberrant Zeb1 expression has been described in a number of other cancers, including colorectal cancer, metastatic lung cancer and aggressive uterine cancer." (PMID 25528765, 2015). "Highly expressed ZEB1 in cancer tissues was also confirmed by IHC staining in 43 IHCC and 64 PHCC specimens as compared with adjacent nontumorous tissues, and was found positively correlated with IHCC and PHCC metastasis." (PMID 25749036, 2015). "A depletion of relevant factors, such as ZEB1, selectively in patients' cancer cells is practically impossible." (PMID 25872941, 2015). "For example, the miR-200 family and miR-205 were shown to contribute to the EMT in cancer cells by directly targeting the transcriptional repressors of E-cad, ZEB1, and ZEB2." (PMID 26110567, 2015). "Taken together, these data underline the relevance of ZEB1/miR-200c regulating MYLK and TKS5 expression in a wide panel of cancer cell lines." (PMID 26334100, 2015). "The ZEB1 transcription factor is best known as an inducer of EMT in cancer metastasis, acting through transcriptional repression of E-cadherin." (PMID 26703648, 2015). "To determine the roles of ZEB1 which is a critical mediator of EMT during cancer progression, we transfected cells with mock and ZEB1 constructs." (PMID 25868853, 2015). "In summary, TKS5 and MYLK represent two mediators of invasive behavior of cancer cells that are regulated by the ZEB1/miR-200 feedback loop." (PMID 26334100, 2015). "Whereas transfection of miR-144 suppressed the migration of cancer cells, co-transfection of Zeb1 attenuated this effect." (PMID 26395400, 2015). "Estrogen, working through ER α, has been shown to up-regulate the expression of ZEB1 in MCF-7 cells, suggesting that increased ZEB1 levels are related to the pro-cancer phenotype promoted by estrogen action within these cells." (PMID 26090296, 2015). "Consistently, β-catenin has been reported to transactivate ZEB1 expression to promote cancer invasion and metastasis, of which the detailed mechanisms will be elucidated in our further studies." (PMID 26036631, 2015). "The transcription factor TWIST1, along with SNAIL1, SLUG and ZEB1, plays the major role in EMT-associated metastasis in cancer cells." (PMID 26023736, 2015). "ZEB1 is a known driver of epithelial-to-mesenchymal transition (EMT), a phenotype associated with cancer cells that are typically prone to metastasis, drug resistance and poor clinical outcome." (PMID 26036631, 2015). "To investigate the role of ZEB1 on S100P-mediated cancer migration and EMT, we inhibited ZEB1 by siRNA transfection, then assessed the expression of EMT markers and cell migration." (PMID 26320193, 2015). "This feedback loop is deregulated in several human cancers including breast, pancreatic, prostate and colon, whereby high ZEB1 and consequently low miR-200 levels are crucial already for the first step of metastasis, the invasion into the surrounding tissues." (PMID 26334100, 2015). "The miR-200 family has also been shown to inhibit the EMT, stimulating the epithelial phenotype and cancer cell migration by direct targeting of the E-cadherin transcriptional repressors ZEB1 and ZEB2." (PMID 25970424, 2015). "Given the role of ZEB1 in mediating resistance to different types of cancer drugs, overexpression of one of its major target genes, miR-203, can efficiently restore drug sensitivity." (PMID 25872941, 2015). "TKS5 and MYLK represent two effectors/mediators of the invasive behavior of cancer cells that are regulated by the ZEB1/miR-200 feedback loop." (PMID 26334100, 2015). "Zeb1/2, Snai1/2 and Twist1 have recently been described as targets of the Fbxo45 containing ubiquitin ligase complex in cancer cell lines." (PMID 26068074, 2015).
cancer (continued). "In contrast, cancer cell express a high base level of ZEB1, a protein that has been shown to be a crucial promoter of malignant tumor progression." (PMID 24967704, 2014). "Binding of ZEB1 and ZEB2 to the E-cadherin E-boxes has been implicated in the regulation of E-cadherin expression in multiple human cancers." (PMID 25197668, 2014). "The Wnt/β-catenin signal pathway promotes EMT in cancer, and miR-200a was found to inhibit Wnt/β-catenin by targeting ZEB1 and ZEB2." (PMID 24598126, 2014). "Binding of ZEB1 and ZEB2 to the spaced E-cadherin E-boxes has been implicated in the regulation of E-cadherin expression in multiple human cancers." (PMID 25197668, 2014). "SNAI1 has also been reported to increase the expression of mesenchymal markers Vimentin and Fibronectin as well as other proteins involved in cancer invasion such as metalloproteinases 2 and 9, and various transcription factors such as ZEB-1 and LEF-1." (PMID 24565133, 2014). "For example, in one study, overexpression of Stat3, PDGF-D, Notch-1, and DCLK1 in cancer cells led to significant downregulation of miR-200 family members; this resulted in up-regulation of ZEB1, ZEB2, and SNAI2 expression and acquisition of the EMT phenotype." (PMID 24598126, 2014). "With respect to the mixed TF-sponge module, it is worth noting that the only remaining interaction - found in cancer cells - is the anti-correlation between mir-141 and its validated target ZEB1." (PMID 25033876, 2014). "The loss of E-cadherin expression results in EMT and cancer metastasis, and E-cadherin has been shown to be inhibited by several EMT regulators, including SNAIL, TWIST, ZEB1, and ZEB2." (PMID 25431208, 2014). "Meanwhile, ZEB1 can directly suppress miRNA-200 family members in cancer cells, including miR-141 and miR-200c." (PMID 24598126, 2014). "The expression level of E-cadherin and ZEB1 is a useful indicator of cancer cell sensitive to target therapy including epidermal growth factor receptor (EGFR) tyrosine kinase inhibitors, gefitinib, and erlotinib." (PMID 25197668, 2014). "The miR-200 family regulates negatively EMT and cancer cell migration in many different epithelial tumors by targeting ZEB1 and ZEB2, which act as transcriptional repressors of E-cadherin." (PMID 25058589, 2014). "The results of recent studies suggest that members of the miR-200 family play a critical role in suppressing EMT and cancer invasion and metastasis by targeting transcriptional repressors of ZEB1 and ZEB2." (PMID 24598126, 2014). "Several target genes of miR-200a have been identified by comparing normal and cancer epithelial cells, such as ZEB1, ZEB2, SIRT1, and KEAP1." (PMID 23750238, 2013). "Using IBC as a prototype pre-clinical model for elucidating the role of MET in aggressive cancer, we manipulated the levels of E-Cadherin via shRNA knockdown and over-expression of ZEB1, a known transcriptional repressor of E-Cadherin." (PMID 23530113, 2013). "A potential explanation is that ZEB1-positive cancer stem cells generate large numbers of rapidly dividing progenies, which in turn drive classification." (PMID 23818228, 2013). "ZEB-1 expression was immunohistochemically categorized as positive if at least 1% cancer cells exhibited nuclear staining." (PMID 24304617, 2013). "Zinc finger E-box binding homeobox 1 (ZEB1) has been shown to promote invasion and metastasis in several types of human cancer and to have a prognostic role in certain cancers." (PMID 23420790, 2013). "The ZEB1 transcription factor is best known as an inducer of epithelial-mesenchymal transitions (EMT) in cancer metastasis, acting through transcriptional repression of CDH1 (encoding E-cadherin) and the EMT-suppressing microRNA-200s (miR-200s)." (PMID 23667256, 2013). "An additional level of adhesion regulation is established by the ZEB1/miR-200 feedback loop that controls cellular plasticity in cancer cells." (PMID 23667256, 2013).
cancer (continued). "To test the roles of OVOL-TFs in MET, as well as the potential function of OVOL2 as a transcriptional repressor of ZEB1, we correlated our RNA-seq results with gene expression in multiple cancer cell lines (Barretina study)." (PMID 24124593, 2013). "The induction of EMT is mediated by a set of key transcription factors within the cell, including Twist, Snail, Snug, Zeb1 and Zeb2, many of which are frequently over-expressed in cancer cells." (PMID 23174018, 2012). "Recent studies have also identified the miR-200 family as a powerful marker and determining factor of the epithelial phenotype of cancer cells by targeting the E-CADHERIN repressors ZEB1 and ZEB2." (PMID 22876288, 2012). "Members of this family, especially miR-200c, inhibit the metastatic ability of cancer cells by targeting the transcriptional repressor zinc-finger E-box binding homeobox 1 (ZEB1) in CRC." (PMID 23091478, 2012). "A decreased miR-141 level promotes the drift into metastatic behaviour of cancer cells, due to repression of miR-141 by ZEB1." (PMID 21827717, 2011). "Zeb-1 transcription was significantly inhibited in pancreatic CSCs and cancer cell lines upon treatment with SAHA." (PMID 21909380, 2011). "Characterization of the normal regulation of tcf8 and expression of ZEB1 is essential for understanding its aberrant expression in various carcinomas, including PCa." (PMID 22190929, 2011). "After characterization of its functions in development, a role for ZEB1 in EMT of cancer cells, invasion and metastasis became a focus of research." (PMID 24281177, 2010). "The role of these miRNAs in cancer progression is based in part on their capacity to target the EMT activators ZEB1 and ZEB2, two transcription factors, which in turn repress expression of E-cadherin." (PMID 20682048, 2010). "In turn, Zeb1 is regulated via the Zeb1/miR200 feedback loop, which is thought to drive cancer progression via promoting EMT and inhibiting senescence." (PMID 20975209, 2010). "Conversely, there are several reports that miR-200 family members and miR-192 can be down-regulated by TGF-beta, and this promotes EMT in cancer and other cell lines via subsequent up-regulation of targets ZEB1 and ZEB2 to repress E-cadherin." (PMID 21049046, 2010). "ZEB1 is normally only expressed in cells of mesenchymal origin; however, its aberrant expression is observed in cancers that have undergone EMT." (PMID 20049172, 2010). "Another early study found ZEB1 to be upregulated in the context of Snail-induced EMT in human carcinoma cells." (PMID 24281177, 2010). "Epithelial–mesenchymal transition (EMT) is a key process in CRC progression and metastasis, characterized by the loss of epithelial markers (e.g., E-cadherin) and the gain of mesenchymal markers (e.g., vimentin and ZEB1), enhancing cancer cell migration and invasion." (PMID 40969596, 2025). "Interestingly, pan-cancer analysis showed that ZEB1 was upregulated only in KIRC but expressed at low levels in the other two types of RCC." (PMID 40074730, 2025). "Zeb1 has been proposed as a promoter of cancer cell stemness." (PMID 40806166, 2025). "Underlying these processes, cancer cells overexpressing FSTL3 exhibited increased expression of the genes associated with epithelial-mesenchymal transition (Vim, Zeb-1, Snai1/2) and extracellular matrix organization (Ecm1), while expression of epithelial markers (Epcam, Cdh1) decreased." (PMID 41029436, 2025). "Cancer cell lines with high ZEB1 expression showed increased mitochondrial fission marker Drp1 and larger total mitochondrial mass, preserved membrane potential with reduced mitochondrial ATP production and respiration, resulting in an overall reduced mitochondrial fitness." (PMID 40830586, 2025). "High ZEB1/2 levels correlate with poor prognosis in various cancers." (PMID 40361472, 2025).
cancer (continued). "The finding that M13SV1-EGFP-Neo Snail-KO cells had a significantly enhanced colony formation capacity may be related to Zeb1 up-regulation, which has been suggested as a promoter of cancer cell stemness." (PMID 40806166, 2025). "Also the zinc finger genes Znf384, which are associated with cancer EMT and metastasis and Zeb1 transactivation were highlighted." (PMID 41446274, 2025). "In CRC, ZEB1 is elevated and related to late-stage cancer metastasis and a poor prognosis." (PMID 40918458, 2025). "ZEB1 expression is upregulated in epithelial tissues to promote cell migration or epithelial-to-mesenchymal transition during pathological processes such as cancer, chronic inflammation, or tissue repair." (PMID 40016707, 2025). "Furthermore, we provide evidence that artesunate exerts its antitumor effects by modulating OGA-mediated O-GlcNAcylation of ZEB1, a key transcription factor involved in cancer progression." (PMID 40771411, 2025). "The mechanisms through which cancer (stem) cells enter and maintain this hybrid/mixed E/M state are not yet clear, but mathematical modeling suggests that this state is likely regulated by the “miR-34-5p-Snail” and “miR-200c-3p-Zeb1” core EMT networks." (PMID 40806166, 2025). "This indicates that targeting ZEB1 could serve as a promising therapeutic strategy for this type of cancer." (PMID 40771905, 2025). "Both results support the notion that ZEB1 suppresses CDS1 expression in mesenchymal-like cancers." (PMID 40615674, 2025). "Interestingly, both miR-409-3p and miR-381-3p are predicted to target ZEB1, and miR-409-3p has been confirmed to target ZEB1 in multiple cancer cells." (PMID 40674434, 2025). "However, our results, both from this study and those recently published, further suggest that Zeb1 is also involved in mediating the stemness capabilities of cancer cells." (PMID 40806166, 2025). "ZEB1 is very important in the change from normal cells to cancer cells." (PMID 40699660, 2025). "Transcription factor ZEB1 is one of the potential master regulators of melanocytes plasticity, because it is recognized as a “driver” of epithelial-to-mesenchymal transitions (EMTs) in carcinomas." (PMID 41226394, 2025). "The most well‐known EMT‐TFs in various cancer types are ZEB1 and Snail." (PMID 39362647, 2024). "The others mapped to areas associated with cancer including FOXP1 (rs1288980) and ZEB1 (rs7349)." (PMID 38493193, 2024). "Additionally, SARS-CoV-2 infection increases the expression of ZEB1 associated with EMT, further highlighting the impact of the virus on cancer-related processes." (PMID 39770330, 2024). "In many cancers, the loss of E-cadherin is attributed to transcription factors such as SNAIL, SLUG, TWIST, ZEB1, and ZEB2, which bind to E-box sequences in the promoter region of the CDH1 gene and negatively regulate its expression, often through promoter methylation." (PMID 39728992, 2024). "Interestingly, the intrinsic factor lumican, a small leucine-rich proteoglycan (SLRP) in the cornea, has shown anti-cancer activities by suppressing ZEB1." (PMID 38822380, 2024). "During the spheroid formation stage, OC cells secretes M-CSF to induce TAMs to M2 polarization, and M2-like TAMs induce EMT of cancer cells, characterized by increased expression of mesenchymal markers (including ZEB1, SNAIL and TWIST) and decreased expression of E-cadherin." (PMID 39513610, 2024). "ZEB1 is an important transcription factor with zinc finger clusters, which can regulate the transcription of target genes, and has been confirmed to play a key regulatory role in cancer invasion and metastasis." (PMID 37989078, 2024). "This clinically relevant type of a transient EMT activation by TGFβ also increased the sensitivity to ferroptosis in various epithelial cancer cell types, which could again be attenuated by depletion of Zeb1." (PMID 39009641, 2024). "ZEB1 could also be an important target for many diseases, including cancer, fibrosis, and corneal injury repair." (PMID 38822380, 2024).